MIR133A2 (microRNA 133a-2)
Synonyms: hsa-mir-133a-2; MIRN133A2; mir-133a-2
Gene: MicroRNA gene on chromosome 20 (62,564,912 to 62,565,013, forward strand). Ensembl gene ENSG00000284508.
Gene Ontology:
Biological process: miRNA-mediated post-transcriptional gene silencing
Cellular component: RISC complex
Homologues: Orthologues: macaque mml-mir-133c (100% identical), chimpanzee ptr-mir-133a-2 (99% identical), zebrafish mir133a-1 (81% identical), mouse Mir133a-1 (63% identical), rat Mir3582 (52% identical). Paralogues in human: MIR133A1 (80% identical), MIR133B (64% identical).
Diseases named in the same sentence as MIR133A2 in open-access papers:
MIR133A2 is named in the same sentence as 3 diseases in open-access papers, as found by Europe PMC text mining. Sharing a sentence is not in itself a finding about the gene and the disease. The quoted sentences say what the papers report.
atrial fibrillation (1 paper, 2013). A disorder characterized by an electrocardiographic finding of a supraventricular arrhythmia characterized by the replacement of consistent P waves by rapid oscillations or fibrillatory waves that vary in size, shape and timing and are accompanied by an irregular ventricular response. "We re-sequenced the MIR1-1, MIR1-2, MIR133A1, MIR133A2, and MIR133B genes, that encode the cardiac-enriched miRNAs, miR-1 and miR-133, in 120 individuals with familial atrial fibrillation and identified 10 variants, including a novel 79T > C MIR133A2 substitution." (PMID 23497314, 2013).
Hypertension (1 paper, 2013). The presence of chronic increased pressure in the systemic arterial system. "This variant, a 79T > C substitution in the MIR133A2 gene, was found in a 67-year old female (II-5, Family KB) who had paroxysmal episodes of AF, hypertension and mitral valve disease." (PMID 23497314, 2013).
MIR133A2 also shares sentences with these, for which no sentence is quoted: mitral valve disease (1 paper).